TRIM15 (tripartite motif containing 15)
Diseases named in the same sentence as TRIM15 in open-access papers (continued):
Sharing a sentence is not in itself a finding about the gene and the disease.
tumor (continued). "Mechanistically, TRIM15 directly targeted Keap1 by ubiquitination and degradation, the principal regulator of Nrf2 degradation, leading to Nrf2 escaping from Keap1-mediated degradation, subsequently promoting antioxidant response and tumor progression." (PMID 35534896, 2022). "Mechanistically, TRIM15 destabilized Keap1 via enhancing its ubiquitination and degradation, and accordingly prevented degradation of Nrf2 resulting in activation of Nrf2 pathway, enhanced tumor proliferation and metastasis." (PMID 35534896, 2022). "Furthermore, the tumor-promoting functions of TRIM15 depended on its E3 ubiquitin ligase." (PMID 35534896, 2022). "Given that the oncogenic functions of TRIM15 rely on its enzymatic activity, we speculated that TRIM15 as E3 ubiquitin ligases exerts its function by interacting with certain key oncogenes or regulating tumor-promoting pathways." (PMID 35534896, 2022). "Mechanistically, TRIM15 degrades YY2 through the proteasome pathway, suppressing FOXRED1 transcription and ultimately accelerating tumor proliferation." (PMID 41237333, 2026). "In contrast, a few members including TRIM8, TRIM15, TRIM24, and TRIM40 are characteristically downregulated in CRC and exert tumor-suppressive activities." (PMID 33066016, 2020). "Animal studies showed that simultaneous knockdown of TRIM15 and YY2 counteracted the inhibitory effect of TRIM15 knockdown alone on the proliferative capacity of EAC cells, and the results of tumor oil red O staining indicated that the inhibition of lipid droplet levels was also counteracted." (PMID 41237333, 2026). "Moreover, up-regulated of TRIM15 increased Nrf2 and the target gene NQO1 expression in subcutaneous tumor tissues, an observation not seen with co-expression of TRIM15 with Nrf2shRNA." (PMID 35534896, 2022).
cancer (9 papers, 2018 to 2026). A tumor composed of atypical neoplastic, often pleomorphic cells that invade other tissues. "Functionally, TRIM15 knockdown resulted in decreased cancer cell proliferation and metastasis, whereas ectopic TRIM15 expression facilitated tumor cancer cell proliferation and metastasis in vitro and in vivo." (PMID 35534896, 2022). "TRIM15 directly targeted Keap1 by ubiquitination and degradation, promoting Nrf2 stabilization, and ultimately an increased proliferation and invasion of cancer cells." (PMID 35534896, 2022). "We next investigated the cancer‐related function of TRIM15 in EAC cells." (PMID 41237333, 2026). "In addition, KEGG enrichment and GSEA analyses of the TCGA-KIRC dataset suggested that TRIM15 was closely associated with the VEGF signaling pathway, cancer-related pathways, and the mTOR signaling pathway." (PMID 36670097, 2023). "Our current study disclosed that MEF2C and TRIM15 could promote invasion and metastasis through cancer-related signaling pathways: the MEF2C-activated MAPK signaling pathway and the TRIM15-activated glycosaminoglycan biosynthesis chondroitin sulfate signaling pathway." (PMID 36661663, 2022). "TRIMs 3, 8, 13, 16, 21, 62 are downregulated in many of the main cancers worldwide (breast, gastric, liver, lung, osteosarcoma, prostate, kidney), while some TRIMs are under-expressed in a cancer-specific way (e.g., TRIM15 in gastric cancer, TRIM26 in liver, TRIM58 in lung)." (PMID 33673719, 2021). "According to the regulation efficacy data, the positive regulation of TRIM15 and NHERF1 by CREB1 was reversed from normal to cancer; the negative regulations of TCEAL2, RBPMS2 and FAM20C by CREB1 disappeared; and the negative regulation of FERMT2 was reversed from normal to cancer." (PMID 35421923, 2022). "Remarkably, expression of WT but not mutant TRIM15 significantly increased cancer cell proliferation and invasion." (PMID 35534896, 2022). "In particular, six candidates (TRIM10, TRIM15, TRIM26, TRIM39-RPP21, TRIM62, and TRIM66) are members of the large tripartite motif (TRIM) family that consists of ubiquitin ligases involved in both innate immunity and cancer progression." (PMID 30102725, 2018).
TRIM15 also shares sentences with these, for which no sentence is quoted: breast carcinoma (3 papers); agranulocytosis (1); atherosclerosis (1); colitis (1); digestive system tumor (1); gastric adenocarcinoma (1); hypopharyngeal squamous cell carcinoma (1); melanoma (1); neurodegenerative disease (1); pancreatic ductal adenocarcinoma (1); rectal cancer (1); schizophrenia (1).